EXO1 (exonuclease 1)
Diseases named in the same sentence as EXO1 in open-access papers (continued):
Sharing a sentence is not in itself a finding about the gene and the disease.
lung carcinoma (20 papers, 2012 to 2026). "EXO1 genetic variants have been associated with the risk and prognosis of different types of cancers, including lung cancer 32-37." (PMID 36606188, 2022). "In a Taiwan cohort, it was found that the A allele of Exo1 K589E correlated to an increased risk of lung cancer." (PMID 36275753, 2022). "EXO1 mutations also have been reported concerning different types of tumor and prognosis of cancers, such as breast, ovarian, pancreatic, and lung cancer." (PMID 36277983, 2022). "A bioinformatic analysis study showed that EXO1 was identified as one of the hub genes which were markedly associated with poor prognosis in patients with lung cancer." (PMID 36606188, 2022). "Although many previous studies have investigated EXO1 polymorphism, especially rs1047840, in lung cancer, most of those studies evaluated the relationship between EXO1 rs1047840 and the risk of lung cancer." (PMID 36606188, 2022). "Among such variants, the association of the p.Glu589Lys in EXO1 gene (rs1047840) with cigarette smoking has been described as conferring a significantly increased lung cancer risk, with a reported odds ratio equal to 1.72." (PMID 27902597, 2016). "Interestingly, in agreement with our data, an overexpression of EXO1 has been already reported to be associated with poor prognosis in breast and lung cancers." (PMID 37592220, 2023). "EXO1 K589E polymorphism is associated with the development of lung cancer in Taiwan and China." (PMID 35204661, 2022). "Moreover, large GWAS analysis indicated that specific mutations in EXO1 are more widely occurring in lung cancer, especially in patients with smoking status." (PMID 36277983, 2022). "Previous data have shown that individuals that carry the A allele of EXO1 rs1047840 may have an increased risk of lung cancer and that thesegenetic polymorphisms could be used as a marker for early detection and primary prevention of this type of cancer." (PMID 35740268, 2022). "Additionally, EXO1 Glu589Lys polymorphism and its surrounding regions were potential genetic susceptibility markers of lung cancer in a Chinese population." (PMID 36275753, 2022). "In addition, by the SNP selection using a database for miRNA binding site variants, we could suggest that the rs1047840-induced change in miRNA binding efficiency may be a mechanism of the association between EXO1 rs1047840 and lung cancer." (PMID 36606188, 2022). "Research has revealed that deficiency of the EXO1 gene can heighten susceptibility and chemotherapy resistance in various malignancies, including BRCA, OV, and lung cancer." (PMID 40433389, 2025). "Although PBK, RRM2, and DLGAP5 are also significant in cancer biology, EXO1’s potential impact on lung cancer mechanisms and treatment is particularly noteworthy." (PMID 39777332, 2024). "The methylation level in each of these three merged motifs was significantly negatively correlated with EXO1 expression in our lung cancer samples." (PMID 38544480, 2024). "In this study, we focus on evaluating association between DNA repair polymorphisms of EXO1, RPA1, and prognosis in lung cancer patients whom received platinum-based chemotherapy." (PMID 36277983, 2022). "Our results indicated that EXO1 rs1776148, rs1047840, and RPA1 rs5030740 were significantly associated with prognosis of lung cancer." (PMID 36277983, 2022). "Above all, in DNA repair polymorphisms, there was a significant association between EXO1 rs1776148, rs1047840, RPA1 rs5030740, and prognosis in lung cancer." (PMID 36277983, 2022). "MSH3 rs26279 and EXO1 rs9350 altered survival of 180 lung cancer and 602 lung cancer patients treated with platinum-based chemotherapy." (PMID 30038702, 2018). "Taken together, E2F1 is potentially involved in transcriptional regulation of EXO1 and the reduced methylation of E2F1 binding motifs may increase the ability of E2F1 to bind to EXO1, thereby leading to the activation of EXO1 in lung cancer." (PMID 38544480, 2024).
lung carcinoma (continued). "Despite previous studies indicating a significant upregulation of EXO1 in various cancers, whether its expression levels alter in lung cancer patients remains unknown." (PMID 39777332, 2024). "However, the relationship between EXO1 expression and clinical factors as well as prognosis in lung cancer remains unexplored, necessitating further research to elucidate its role in cancer progression." (PMID 39777332, 2024). "Additionally, in vitro results showed that downregulation of EXO1 inhibited the migratory ability of lung cancer cells." (PMID 36971680, 2023). "In this study, we evaluated whether polymorphisms in DNA damage and repair genes (EXO1, RPA1, PMS1, and PMS2) were associated with prognosis and response to platinum-based chemotherapy in lung cancer patients." (PMID 36277983, 2022). "The genotypes of RPA1 rs5030740, EXO1 rs1776148, and rs1047840 may be a biomarker contribute to predict the prognosis of platinum-based chemotherapy lung cancer patients." (PMID 36277983, 2022). "Consequently, focusing on EXO1 could yield deeper insights into the pathogenesis of lung cancer and identify promising therapeutic targets." (PMID 39777332, 2024). "Also specific to the epithelial compartment, we observed enrichment for a signature conferring poor outcome in lung cancer, which included general cancer prognostic genes like AURKB, EXO1, MAD2L1, CDCA8, and kinesins like KIF15." (PMID 32883324, 2020). "Using CENP-F as a G2/M cell marker, we observed a strongly negative correlation between the expression levels of RBX1 and EXO1 proteins in multiple cell types, including human cervical carcinoma HeLa, breast adenocarcinoma MCF7, lung carcinoma A549, and osteocarcinoma U2OS cells." (PMID 31562368, 2020).
ovarian carcinoma (14 papers, 2014 to 2024). A malignant neoplasm originating from the surface ovarian epithelium. "FOXM1 transcriptional targets linked to platinum resistance in ovarian cancer include exonuclease 1 (EXO1), a DNA repair protein recruited to double-stranded breaks, and PCLAF, a protein that activates the PI3K/AKT/mTOR signaling pathway." (PMID 34205406, 2021). "A previous study reported that overexpression of EXO1 protects ovarian cancer cells from cisplatin‐mediated apoptosis, and inhibition of EXO1 enhances chemotherapy cytotoxicity against ovarian cancer." (PMID 39046429, 2024). "Of note, the expression of EXO1 was associated with resistance to cisplatin and doxorubicin via NHEJ in ovarian cancer, a tumor also sensitive to trabectedin." (PMID 33983674, 2021). "FOXM1 facilitates DNA repair through regulating direct transcriptional target EXO1 (exonuclease 1) to prevent cancer cells from cisplatin-mediated apoptosis as observed in ovarian cancers." (PMID 29932172, 2018). "The network based approach identified two 7-gene functional interaction modules (31: DCLRE1A, EXO1, KIAA0101, KIN, PCNA, POLD3, POLD2; 35: DKK3, FABP3, IRF1, AIM2, GBP1, GBP2, IRF2) that are associated with prognosis of ovarian cancer patients." (PMID 27806724, 2016). "Our studies therefore uncover that the FOXM1/EXO1 axis protects ovarian cancer cells after cisplatin treatment by enhancing the DNA damage repair pathway." (PMID 24824601, 2014). "Attenuating FOXM1 and EXO1 expression by small interfering RNA, augments the chemotherapy efficacy against ovarian cancer." (PMID 24824601, 2014). "We discover that EXO1 is a potential downstream gene of FOXM1 in ovarian cancer, FOXM1 directly binds to EXO1 promoter and enhances EXO1 expression." (PMID 24824601, 2014). "FOXM1 facilitates DNA repair through regulating direct transcriptional target EXO1 to protect ovarian cancer cells from cisplatin-mediated apoptosis." (PMID 24824601, 2014). "Coherently with the role of EXO1 in promoting cGAS positive MN in a SETX deficient background, we found that in ovarian cancer, head and neck squamous cell carcinoma and glioma the concurrent presence of low SETX and high EXO1 expression levels leads to poor survival." (PMID 39120648, 2024). "Moreover, the high expression of EXO1 is related to the resistance of gastric and ovarian cancers to cisplatin." (PMID 37251536, 2023). "EXO1 up-regulated expression could protect ovarian cancer cells from cisplatin-mediated apoptosis, and attenuating EXO1 expression by small interfering RNA could augment the chemotherapy efficacy against ovarian cancer." (PMID 27174663, 2016). "Our findings indicate that targeting FOXM1 and its target gene EXO1 could improve cisplatin effect in ovarian cancer, confirming their role in modulating cisplatin sensitivity." (PMID 24824601, 2014). "Our data suggests that EXO1 mediate FOXM1-activated DSB repair in ovarian cancer." (PMID 24824601, 2014). "In accordance with this hypothesis, we found that FOXM1 knockdown seems more efficient than EXO1 silencing in sensitizing ovarian cancer cells to cisplatin treatment." (PMID 24824601, 2014). "Finally, we demonstrate that EXO1 plays an important role in the DNA repair pathway activated by FOXM1 in ovarian cancer." (PMID 24824601, 2014). "In the present study, we provide the evidences that FOXM1 and its direct downstream DNA repair gene EXO1 might play in increasing the survival of ovarian cancer cells after cisplatin treatment, and targeting FOXM1/EXO1 axis can sensitize ovarian cancer cell to cisplatin treatment." (PMID 24824601, 2014). "In conclusion, we found that FOXM1 directly regulated EXO1 expression to promote the DNA repair pathway upon cisplatin treatment, and demonstrated that FOXM1 knockdown can enhance sensitivity of ovarian cancer cells to cisplatin." (PMID 24824601, 2014). "EXO1 has been reported to be involved in mammalian non-homologous end joining and leads to drug resistance in ovarian cancer." (PMID 35837383, 2022).
ovarian carcinoma (continued). "Recently, EXO1 was reported as being involved in non-homologous end joining and contribute to drug resistance in ovarian cancer." (PMID 34769200, 2021). "Investigations using CRISPR technology to create drug‐resistant ovarian cancer cell lines have demonstrated that the absence of EXO1 can reverse drug resistance and improve sensitivity to cisplatin and doxorubicin, and it was therefore identified as a potential therapeutic target." (PMID 37439040, 2023). "Although EXO1 knock-down did not affect the expression of FOXM1, it did partly recapitulate the cisplatin sensitization effect of FOXM1 silencing in ovarian cancer cells." (PMID 24824601, 2014).
lung adenocarcinoma (11 papers, 2021 to 2026). A carcinoma that arises from the lung and is characterized by the presence of malignant glandular epithelial cells. "Low EXO1 expression in lung adenocarcinoma patients is associated with prolonged survival compared to those with high expression levels." (PMID 39777332, 2024). "In conclusion, two SNPs in miRNA binding sites, especially EXO1 rs1047840G>A, were associated with the treatment response to pemetrexed chemotherapy and survival in lung adenocarcinoma patients." (PMID 36606188, 2022). "In conclusion, two SNPs in miRNA binding sites, especially EXO1 rs1047840G>A, were associated with the chemotherapy response and survival outcome in lung adenocarcinoma patients treated with pemetrexed." (PMID 36606188, 2022). "Finally, a comprehensive analysis of TCGA, GEPIA and Kaplan-Meier Plotter databases revealed that high mRNA expression of CCNB1, CDC25C, CENPM, and EXO1 was associated with poor survival in lung adenocarcinoma patients." (PMID 35646074, 2022). "Expression levels of EXO1 vary across different cancers; for instance, it is elevated in certain tumors such as lung adenocarcinoma, breast cancer, and hepatocellular carcinoma, while reduced in others like neuroblastoma and leukemia." (PMID 39777332, 2024). "Exonuclease 1 (EXO1), a protein involved in mismatch repair and recombination processes, has been identified as a prognostic biomarker in lung adenocarcinoma (LUAD)." (PMID 39777332, 2024). "Additionally, this study employed wound healing assay and CCK-8 cell proliferation assays to investigate the significant role of EXO1 in promoting the growth and migration of lung adenocarcinoma cells." (PMID 39777332, 2024). "These compelling findings reveal the intricate potential molecular mechanisms through which EXO1 may promote both cell growth and migration in lung adenocarcinoma (LUAD), suggesting a multifaceted role in the progression of this disease." (PMID 39777332, 2024). "Additionally, the lack of comprehensive in vivo validation restricts our ability to fully elucidate the functional implications of EXO1 in lung adenocarcinoma progression." (PMID 39777332, 2024). "Besides, exonuclease 1 (EXO1) constitutes a plausible prognostic biomarker and exhibits significant correlations with immune infiltrates in lung adenocarcinoma." (PMID 37325647, 2023). "In this study, EXO1 was significantly upregulated in lung adenocarcinomas with high-grade patterns." (PMID 35204661, 2022). "After intersection with The Cancer Genome Atlas–Lung Adenocarcinoma prognostic genes, three genes, exonuclease 1 (EXO1), family with sequence similarity 83, member A (FAM83A), and disks large-associated protein 5 (DLGAP5), were identified as prognostic gene signatures." (PMID 35204661, 2022). "The acquired data suggest that EXO1 acts as a predictor of poor prognosis in LUAD and facilitates the growth and migration of lung adenocarcinoma cells." (PMID 39777332, 2024). "By bioinformatic analyses using public database, they revealed the correlation between increased EXO1 expression and decreased tumor infiltrating B cells and CD4+ T cells, suggesting that EXO1 may induce an immune-suppressive tumor microenvironment in lung adenocarcinoma." (PMID 36606188, 2022).
colorectal cancer (10 papers, 2005 to 2023). A primary or metastatic malignant neoplasm that affects the colon or rectum. "The simultaneous occurrence of the Lys/Glu genotype of the EXO1 gene and the Pro/Pro genotype of the PolB gene was found to possibly increase the risk of colorectal cancer (OR = 2.265 (1.193–4.301), p = 0.011)." (PMID 26649135, 2016). "Since PMS1, MLH3 and EXO1 have only been implicated in the development of colorectal cancers in case reports, they are unlikely to be implicated in the development of cancer in our group." (PMID 16106253, 2005). "The genotyping results indicate that the Lys/Glu genotype of the EXO1 gene may increase the risk of colorectal cancer (OR = 1.672 (1.109–2.519), p = 0.014)." (PMID 26649135, 2016). "Amygdalin has been proven to lessen the expression of cell cycle-related genes in SNU-C4 colorectal cancer cells, such as exonuclease 1 (EXO1), topoisomerase (DNA) I (TOP1), subfamily F, and ATP binding cassette." (PMID 36618007, 2023). "Our previous study regarding mutations in DNA-repair-associated genes in colorectal cancer demonstrated that EMAST+/MSI-H tumors had a higher frequency of MLH1, MSH3, MSH6, PMS2, and EXO1 genetic mutations than the other three colorectal cancer subtypes." (PMID 32120855, 2020). "Comparing the results of the present study and our previous study in colorectal cancer, we observed that MSH6 and EXO1 genetic mutations were higher in EMAST+/MSI-H tumors than other subtypes, in both GC and colorectal cancer." (PMID 32120855, 2020). "In addition, polymorphisms of EXO1, LIG3, and PolB may modulate the risk of colorectal cancer by decreasing (PolB) or increasing (LIG3 and EXO1) the chance of malignant transformation." (PMID 26649135, 2016). "Considering the role of rs72755295 on EXO1 expression regulation, this SNP might contribute to the difference in platinum salts response among cancer patients, which has been preliminarily verified by a recent pharmocogenetics study in advanced colorectal cancer and deserves further research." (PMID 36255267, 2022). "On the other hand, our literature search did not identify reports of germline PVs in EXO1 or NEIL1 in OC, although variants in these genes have been reported in the context of other hereditary cancers such as colorectal cancer." (PMID 36969007, 2023). "EXO1 also plays an essential role in hereditary nonpolyposis colorectal cancer and its atypical forms." (PMID 34769200, 2021).
prostate carcinoma (10 papers, 2015 to 2025). A carcinoma that arises from epithelial cells of the prostate gland. "Nonetheless, CRAVAT reported that mutations in EXO1 have been observed also in prostate cancer, highlighting the potential role of this gene for this malignancy." (PMID 28206966, 2017). "Interestingly, mutations in EXO1 have been observed also in prostate cancer, highlighting the potential role of this gene for this malignancy." (PMID 28206966, 2017). "We found that EXO1 geneexpression was elevated in multiple types of cancer, including hormone-relatedbreast, ovarian, and prostate cancers." (PMID 40378357, 2025). "Immune infiltration analysis showed that EXO1 promoted infiltration of activated CD4+positive T cells in multiple tumor types including prostate cancer." (PMID 38279172, 2024). "In our study, we discovered that EXO1 acts as a novel biomarker of PCa, which promotes prostate cancer progression by regulating lipid metabolism reprogramming in prostate cancer cells." (PMID 38279172, 2024). "EXO1 was involved in tumor mutational burden (TMB) and its clinical significance in prostate cancer." (PMID 36971680, 2023). "Polymorphic changes among two genes CDH1 (-160C/A) and Exo1 (K589E), have been identified as a crucial parameter for the development of prostate carcinoma, as reported in a study of 100 patients." (PMID 35326902, 2022). "Furthermore, prostate cancer patients were classified into four different immune subtypes (C1, C2, C3, and C4), and EXO1 expression was found to be the lowest in the C3 subtype." (PMID 38279172, 2024). "Consistent with previous findings in prostate cancer, these results collectively indicate that EXO1 may act as an oncogene in the progression of malignant tumors, resulting in a worse prognosis." (PMID 39777332, 2024). "It was found that the abnormal expression of EXO1 gene may affect the prognosis, survival and progress of patients with prostate cancer." (PMID 35449547, 2022). "miR-31 has a known role in prostate cancer and melanoma, suppressing key cell cycle regulators and pro-oncogenic genes such as CDK1, E2F2, EXO1, FOXM1, MCM2, Src or MET." (PMID 25644061, 2015). "We found that EXO1 promoted BCL2, CDC25, and PCNA and inhibited BAX expression, and further experiments showed that EXO1 inhibited apoptosis in prostate cancer cells." (PMID 38279172, 2024).
hepatocellular carcinoma (9 papers, 2016 to 2024). A malignant tumor that arises from hepatocytes. "EXO1 is also thought to play a role in the progression of hepatocellular carcinoma, and its high expression levels have been found to be positively related to tumour migration, invasion, and lymph node metastasis." (PMID 39046429, 2024).